HLA-G (major histocompatibility complex, class I, G)
Diseases named in the same sentence as HLA-G in open-access papers (continued):
Sharing a sentence is not in itself a finding about the gene and the disease.
tumor (continued). "HLA-G could also enhance the expression of matrix metalloproteinases (MMPs) which are tumor metastasis-related factors favoring tumor progression." (PMID 39766165, 2024). "Tumor cells employ HLA-G overexpression to evade host immune surveillance during carcinogenesis." (PMID 39703498, 2024). "It was found that the tumor-infiltrating CD8+ ILT2+ T cells’ cytotoxic functions could be selectively inhibited by HLA-G expression by tumor cells." (PMID 39594832, 2024). "However, data concerning the consequence of HLA-G expression in tumor cells are far from being available even though high incidence of HLA-G expression has been reported in several tumors such as ccRCC." (PMID 39358558, 2024). "Hence, a growing body of preclinical work attempts to unveil novel approaches to break the HLA-G-based shield adopted by tumors to restore the anti-tumor response of immune effector cells, advancing future clinical applications." (PMID 38310272, 2024). "It has been shown that nocodazole and CDK1 inhibitors, but not lovastatin, could cause cell cycle blockade accompanied by increased expression of HLA-G and PD-L1, which impaired the killing effect of immune cells against tumor cells." (PMID 38310272, 2024). "Strategies such as miRNA-mediated downregulation of HLA-G expression or inhibition of its interaction with its cognate receptors, akin to current PD-1/PD-L1 immunotherapies, hold promise for stimulating immune responses against the tumor." (PMID 39549048, 2024). "HLA-G can inhibit many players associated with the anti-tumor response throughout early and late tumor stages, although CTLA-4 and PD-1 are predominantly expressed in higher tumor grades." (PMID 38450191, 2024). "HLA-G facilitates the escape of tumor cells from immunosurveillance by various mechanisms." (PMID 39594832, 2024). "Recognizing the presence and collaboration of multiple ICPs and the challenges posed by adaptive resistance when solely targeting the PD‐1/PD‐L1 pathway,[7a,b] we developed Nb‐TriTE with a novel construct containing VHH fragments directed toward PD‐L1 and HLA‐G on tumor cells." (PMID 39234811, 2024). "GEPIA was used to obtain the expression of HLA-G in tumor tissues and corresponding normal tissues." (PMID 37875821, 2023). "However, in various malignancies, HLA-G expression is abnormally upregulated, which leads to tumor immune evasion, dissemination, and unfavorable clinical outcomes." (PMID 37048814, 2023). "Tumor cells at the invasion front induce the increase of SPP1+ macrophages by expressing high levels of HLA‐G, and SPP1+ macrophages secrete IL‐1β to recruit additional SPP1+ macrophages, and together they inhibit anti‐tumor immunity by depleting other immune cells." (PMID 37632718, 2023). "Interestingly, in vitro studies have shown that just 10% of HLA-G+ tumor cells is sufficient to protect the rest of the tumor cells from elimination by CTLs, highlighting the strong regulatory capabilities of HLA-G in tumor promotion." (PMID 38067396, 2023). "Expectedly, LILRB1 ligation by HLA-G on tumour cells induces tumour immune-evasion." (PMID 38022598, 2023). "Regarding BC, HLA-G expression has been detected in tumor tissues in about 66% of patients." (PMID 37283737, 2023). "Based on these findings, we associated each of the studied mutations (individually and in combination) with tumor expression of HLA-G; however, we did not observe such associations." (PMID 37569841, 2023). "In the context of cancer, HLA-G has been shown to confer protection to cancer cells against the cytotoxic activity of natural killer cells and cytotoxic T lymphocytes, enabling tumor immune escape, promoting tumor proliferation, and correlating with reduced patient survival." (PMID 37627278, 2023). "The observed prognostic effect of HLA-G expression may be attributed to its tolerogenic properties, which could provide a potential mechanism for evading immunosurveillance and promoting tumor progression." (PMID 37048814, 2023).
tumor (continued). "Notably, HLA-G was correlated with the levels of TILs, including CD4+ T cells, CD8+ T cells and MDSCs, which suggested that HLA-G plays an important role in the tumor environment." (PMID 37875821, 2023). "The activation of immune inhibitory proteins such as PD-L2 and HLA-G may favor tumor escape from the immune system and partially explain the poor prognosis of ACC." (PMID 36835997, 2023). "Furthermore, TISIDB was used to investigate the correlation between HLA-G expression and tumor-infiltrating lymphocytes (TILs), including activated CD4+ T cells, CD8+ T cells, MDSCs and Tregs." (PMID 37875821, 2023). "Both local modulatory factors and individual genetic features may account for the increased expression of HLA-G in the tumor microenvironment." (PMID 37629044, 2023). "As for sHLA-G, HLA-G-EV’s role in tumor immune escape is well-described." (PMID 36768880, 2023). "Therefore, HLA-G plays a crucial role in the tumor microenvironment by inhibiting the functions of effector cells and increasing MDSCs as well as Tregs." (PMID 37875821, 2023). "The acquisition of HLA-G through trogocytosis represents a potential tumor escape strategy." (PMID 37974170, 2023). "The sHLA-G over expression in patients with polyps could be explained by the fact that HLA-G is crucial for tumor immune evasion and malignant transformation." (PMID 37573450, 2023). "The differentially expressed miRNAs targeting the BRAF and/or HLA-G genes may explain their increased expression in the tumor milieu." (PMID 37569841, 2023). "Considering that the expression level of PD‐L1 may be a bottleneck for the application of Nb‐CAR‐γδT in the treatment of solid tumors, we analyzed the expression pattern of PD‐L1 and HLA‐G in tumor lesions of NSCLC and TNBC patients." (PMID 37078788, 2023). "For example, HLA-G expression is altered in non-Hodgkin B-lymphoma and correlates to tumor relapse and transformation, but this feature has been postulated to be associated to the deep genetic disorder and rearrangement that, in turn, induces HLA-G neo-expression." (PMID 35328349, 2022). "In addition, the poor prognosis in tumor patients was confirmed to be closely related to abnormal HLA-G expression, which most likely helped the tumor to escape from immunotherapy." (PMID 37078002, 2022). "Based on the restricted tissue expression pattern and immunosuppressive functions of HLA-G molecule, many recent studies have consistently claimed that HLA-G could be a new immune checkpoint molecule in tumours." (PMID 35924232, 2022). "In this way, HLA-G can be transferred from tumor cells to activated NK cells or to monocytes." (PMID 35185904, 2022). "Thus, in the end, HLA-G contributes to the metastatic spread and to the evolution of aggressive tumor cells in different solid and hematological tumors." (PMID 35328349, 2022). "The presence of HLA-G in tumors has been described in several studies, some of them emphasizing that it is only present in tumor and not in distal/healthy tissue, a finding that would reinforce the idea of the participation of HLA-G in tumor development and progression." (PMID 35154112, 2022). "Omitting early reports applying only RCC cell lines, studies analyzing RCC patient cohorts could demonstrate a statistically significant correlation between HLA-G expression and higher tumor grading and staging in RCC patients using IHC and ELISA." (PMID 35185904, 2022). "Importantly, they found that the number of tumor-infiltrating NK cells was significantly lower in HLA-G (+) tumors compared to HLA-G (–) tumors (p<0.001), emphasizing the inhibitory role of this molecule." (PMID 35154112, 2022). "HLA-G plays a great role in creating a tolerogenic tumor microenvironment." (PMID 35626255, 2022).
tumor (continued). "In numerous in vitro studies, the downregulation of HLA-G protein levels, e.g. by overexpression of HLA-G regulatory miRs, by HLA-G-specific CRISPR/Cas9 systems or by simple inhibition of HLA-G with antibodies, resulted in an increased lysis of tumor cells by immune effector cells." (PMID 35185904, 2022). "Since primary NB cells tested negative for HLA-G expression, we hypothesized that the metastatic spread of NB cells may be paralleled by the de novo expression of HLA-G on tumor cells." (PMID 35328349, 2022). "We defined HLA-G-positive tumours as 10 or more positive cells in one full slide, which may be a very low cut-off." (PMID 35027037, 2022). "Later investigations have established that HLA-G is an important marker of tumor immune escape." (PMID 35185887, 2022). "However, some studies have suggested that HLA-G can be recognized as a potential immune checkpoint that promotes tumor immune escape." (PMID 36189298, 2022). "It has been suggested that HLA-G expression can be involved in the immune editing process, which is defined by three distinct stages of immune responses and the interaction between tumor cells with their microenvironment: the elimination, equilibrium and escape." (PMID 35185904, 2022). "Soluble HLA-G released by tumor cells interacts with NK cell receptors and CD8+ T cell receptors and even may cause apoptosis of immune effector cells as well as the functional inhibition of immune effector cells." (PMID 35185904, 2022). "Finally, hypoxia upregulates the expression of immunosuppressive HLA-G on the surface of tumor cells." (PMID 35910347, 2022). "These TILs did not express CD25 and CD69 activation markers within the HLA-G positive group confirming the hypothesis that HLA-G expression might contribute to the immune evasion of the tumor cells by inhibition of immune effector cells." (PMID 35185904, 2022). "On the basis of these observations, we discuss future possible therapeutic strategies based on the combination of (i) blocking antibodies against HLA-G or its receptors and (ii) blocking antibodies specific for other IC molecules, with the aim of fully restoring anti-tumor immune response." (PMID 35328349, 2022). "Meanwhile, Urosevic and colleagues made an editorial comment, proposing that HLA-G and related killer cell inhibitory receptor might represent another mechanism for tumor immune escape." (PMID 35185887, 2022). "Therefore, exploring the relationship between HLA-G-positive tumours and their driving DEGs or their impact on the tumour microenvironment is very important for developing effective immunotherapy strategies." (PMID 35924232, 2022). "HLA-G can induce local temporary immunosuppression, inhibit autoimmune or infection-related inflammatory responses, and down-regulate immune responses, such as anti-tumor responses." (PMID 36176778, 2022). "In addition, as a potential tumour marker, HLA-G can predict the diagnosis and prognosis of various types of cancer." (PMID 35924232, 2022). "The propensity for HLA‐E expression in malignant cells is still not fully understood, and it has been suggested that tumours may upregulate HLA‐E and HLA‐G to escape killing by immune cells." (PMID 35596615, 2022). "Emerging evidence indicates that tissue expression of HLA-G, as well as HLA-G-expressing regulatory cells, and the level of soluble HLA-G may play an important role in dictating the outcome of the anti-tumor immune response." (PMID 35626255, 2022). "Therefore, HLA-G and the downstream signaling pathways upon interaction with its cognate receptors can be soundly considered a new target for immune-based anti-tumor therapy." (PMID 35154112, 2022). "Yang’s team reported that there were more cases with high expression of HLA-G in non-luminal than in luminal subtypes, and HLA-G expression was associated negatively with the density of tumor-infiltrating lymphocytes." (PMID 35185887, 2022).
tumor (continued). "Indeed, tumor cells expressing high levels of HLA-G are able to suppress anti-tumor responses, thus escaping from the control of the immune system." (PMID 35328349, 2022). "Interestingly, the process of placentation bears several striking similarities to tumor cell metastasis, and both trophoblasts and tumor cells express immunosuppressive molecules, including HLA-G and PD-L1." (PMID 36138021, 2022). "HIF-1a expression is high in neoplasia, and it is responsible for the suppression of tumor cells by inducing NO synthesis, CD 47, PD-L1, and HLA-G overexpression in the tumor microenvironment, overregulation of ADAM 10 metalloproteinase expression, and adenosine increases." (PMID 36294785, 2022). "Furthermore, HLA-G is involved in the relationship between immune system, tumor cells, and their microenvironment and in all three stages of tumor progression (i.e., elimination, equilibrium, and escape), as described in the Schreiber’s theory." (PMID 35328349, 2022). "The mAbs may bind to different epitopes, which may influence the detection rate of HLA-G isoform expression in different tumours." (PMID 35027037, 2022). "In addition, HLA-G is expressed on tumor-infiltrating cells, especially on lymphocytes, monocytes, macrophages, and DC, and its clinical relevance is undisputed due to the following considerations." (PMID 35328349, 2022). "However, contrasting data have been reported regarding the role of tumor cell HLA-G expression in the CRC setting." (PMID 35902421, 2022). "Otherwise, tumor cells in hypoxia could inhibit TAMs activation via HLA-G/LILRB interactions, assist TAMs polarization via CD44-related communication, and inhibit T-cell activation via PDCD1 and TIGIT." (PMID 34956900, 2021). "They observed that 33% of the tumour samples expressed high levels of HLA-G." (PMID 34361031, 2021). "In addition, The HLA-G molecules on tumor cells can be transferred to monocytes and T cells via trogocytosis." (PMID 33668117, 2021). "We also used the well-known DNMT1 inhibitor 5-aza45 to address whether DNMT1 regulates cell surface HLA-G expression of tumor cells and evaluated its effect on subsequent CAR-NK challenge." (PMID 34663641, 2021). "However, under pathological conditions, HLA-G has been detected in many types of primary tumors and metastases at a variable frequency and is strongly related to high tumor grade and poor prognosis for cancer patients." (PMID 34276642, 2021). "In addition to HLA-G expressed on tumor cells, intercellular transfer of tumor cell-derived HLA-G molecules through trogocytosis, exosomes and tunnelling nanotubes (TnTs), which represents another important complementary mechanism for cancer cell escape." (PMID 34276642, 2021). "Remarkably, HLA-G expression was also observed in the tumour stroma." (PMID 34361031, 2021). "Upregulation of HLA-G may provide tumour cells with protection from NK cell-mediated cytotoxicity as HLA-G inhibits NK cell function." (PMID 34361031, 2021). "In addition, autocrine TGF-β signaling in tumor cells also promoted the expression of HLA-G, which bound to KIR2DL4 and enabled tumor cells to inhibit the activation of NK cells." (PMID 34158475, 2021). "Given that CD86 and HLA-G are transferred from tumor cells via trogocytosis, trogocytosis of these molecules by CD8+ T cells may play a suppressive role in tumor immune responses." (PMID 34069602, 2021). "In total, 209 out of 525 patients (40%) had either low or strong tumour HLA-G expression." (PMID 34361031, 2021). "In cancer, abnormal expression of HLA-G is considered a key strategy of tumor cells to evade immune surveillance, which is strongly supported by the high incidence of tumors in patients treated with immunosuppressive agents after organ and stem cell transplantation." (PMID 34868081, 2021). "Therefore, HLA-G can be shedding from the cell surface by metalloproteases or released from various cells, incorporated into EVs, and serve as a promising tumor indicator." (PMID 34868081, 2021).
tumor (continued). "In addition to having a low tumor mutation burden, Ewing sarcomas are, in many cases, noted to have a low expression of Human Leukocyte Antigen (HLA) class I and to have acquired expression of the immunosuppressive HLA-G molecule at the surface of tumor cells." (PMID 34440251, 2021). "After disproving a direct inhibitory interaction between the HLA-G-positive EwS cells and tumor-antigen specific CART, we addressed the hypothesis that myeloid bystander cells in the TME can mediate the T-cell inhibitory effects of HLA-G in this cancer." (PMID 34201079, 2021). "Thus, it seems that tumour HLA-G expression, clinicopathological parameters indicative for tumour burden, and clinical outcome of patients are interrelated." (PMID 34361031, 2021). "Additionally, positive correlations between tumour HLA-G expression and clinicopathological parameters such as tumour stage, LNM and distant metastasis were only observed in the tumour parenchyma and not in the stroma." (PMID 34361031, 2021). "Nevertheless, there is a subpopulation in most tumor types with elevated HLA-G mRNA expression." (PMID 34663641, 2021). "In this context, the cytotoxic functions of tumor-infiltrating CD8+PD-L1-ILT-2+ cells could be selectively inhibited by tumor cell-expressing HLA-G." (PMID 34054869, 2021). "However, an aberrant induction of HLA-G expression is observed in most cancer histological types, which is closely related to tumor metastasis and poor prognosis in clinical settings as well as in murine laboratory models." (PMID 34054869, 2021). "Tumours expressing HLA-G had a significantly higher frequency of CD3+ and CD8+ T cells." (PMID 34439175, 2021). "Whether these data are consistent with the levels of tumor cell surface HLA-G expression remain elusive." (PMID 34276691, 2021). "Furthermore, tumour HLA-G expression was positively correlated with the Treg/CD8+ ratio, which signifies a potential functional role of HLA-G in modulating the immune-tumour response." (PMID 34361031, 2021). "Other approaches to measure HLA-G in tumour lesions could include using HLA-G mRNA expression levels." (PMID 34361031, 2021). "One strategy successfully deployed by cancer cells for immune evasion is the impairment of the classical HLA class I and II antigens to hide infected cells from T cell recognition, while aberrant induction of HLA-G expression by cancer cells makes host anti-tumor immune system rather vulnerable." (PMID 34276691, 2021). "If this would be the case then HLA-G expression does not have a causal, functional role in tumour progression and therefore poor clinical patient outcome, but would rather be the consequence of these tumours possessing an aggressive phenotype." (PMID 34361031, 2021). "Furthermore, we also investigated how CAR converted inhibitory HLA-G to activating signal and explained the mechanism of chemotherapy induced cell surface HLA-G on tumor cells." (PMID 34663641, 2021). "Or rephrased, has HLA-G an active, functional role in tumour progression which leads to poor clinical patient outcome or is HLA-G expression a by-product of an increased genomic instability in the tumours of patients with poor clinical outcome?" (PMID 34361031, 2021). "We speculate that HLA-G expression may indirectly recruit immune cells by regulating the secretion of cytokines in the tumor microenvironment." (PMID 34276642, 2021). "In the TME, lncRNAs regulate expression of molecules (e.g. PD-L1, MHC I, and HLA-G) on the surface of the tumor cells, which may help attenuate the function of effector T cell." (PMID 34880875, 2021). "As such, 50% of the tumour samples expressed high levels of HLA-G (IRS ≥ 2)." (PMID 34361031, 2021). "Studies showing inverse relationships between HLA-G expression and clinicopathological parameters associated with increased tumour burden showed prolonged survival or statistically non-significant poor clinical outcome associated with HLA-G expression." (PMID 34361031, 2021).